BTLA (B and T lymphocyte associated)
Diseases named in the same sentence as BTLA in open-access papers (continued):
Sharing a sentence is not in itself a finding about the gene and the disease.
type 1 diabetes (5 papers, 2014 to 2025). "IFN‐γ‐primed platelets enriched with immunosuppressive ligands (PD‐L1, PD‐L2, BTLA, and Gal‐9) are shown to induce T cell exhaustion and apoptosis, preserving β‐cell function and preventing hyperglycemia progression in type 1 diabetes." (PMID 40019367, 2025). "BTLA plays a regulatory role in peripheral tolerance, evidenced by the ability of BTLA+ DCs to induce CD8+ T cell tolerance that could alleviate the severity of type 1 diabetes." (PMID 36159789, 2022).
diabetes (4 papers, 2011 to 2017). "This study has shown that the onset of diabetes is delayed when anti-BTLA mAb is given to 10-week-old NOD mice." (PMID 22997525, 2012). "In addition, anti-BTLA mAb inhibits anti-PD-1 mAb-induced acceleration of diabetes in NOD mice." (PMID 22997525, 2012). "Apart from this genetic link between diabetes and IL-12/IL-23p40, immunological studies have demonstrated that therapies enhancing BTLA-negative co-signalling may be a potential therapeutic target in treating autoimmune diabetes." (PMID 22185520, 2011).
esophagogastric junction adenocarcinoma (4 papers, 2019 to 2022). "Furthermore, the correlation of patients smoking status with the frequency of BTLA SNPs was also observed in esophagogastric junction adenocarcinoma (EGJA)." (PMID 36741370, 2022).
glioblastoma (4 papers, 2023 to 2025). The most malignant astrocytic tumor (WHO grade IV). "Similarly, previous preclinical investigations have shown that checkpoint blockade combined with PD-1 and BTLA can exert synergistic antitumor effects by directly activating CD4+ and CD8+ T cells in glioblastoma." (PMID 40463377, 2025). "Interestingly, dual BTLA/PD-1 blockade showed heightened IFN-γ levels and improved overall survival compared to monotherapies in murine models of glioblastoma." (PMID 37041226, 2023).
Listeria infection (4 papers, 2011 to 2021). "The common phenotype of a reduction in antigen-specific CD8+ T cells in BTLA- and HVEM-deficient mice suggests that the BTLA-HVEM pathway plays a role in the survival of antigen-specific CD8+ T cells after Listeria infection." (PMID 24205057, 2013). "In mice, it was recently shown that B- and T-lymphocyte attenuator (BTLA) (another co-inhibitory molecule) was induced at the early phase of Listeria monocytogenes infection." (PMID 21418617, 2011). "Based on these data, we hypothesized that during Listeria infection, BTLA expression in the host might promote the survival of effector CD8+ T lymphocytes by interacting with HVEM expressed by T cells." (PMID 24205057, 2013). "We clearly demonstrated that the function of the BTLA-HVEM pathway is not limited to inhibitory signaling in the responding T lymphocytes, as BTLA expressed in “trans” by cells other than T lymphocytes promoted the survival and accumulation of HVEM+CD8+ T cells during Listeria infection." (PMID 24205057, 2013). "Furthermore, HVEM expression in CD8+ T lymphocytes and BTLA expression in other cell types are necessary for the optimal survival of effector and memory T cells, suggesting that the BTLA/HVEM pathway enhances activated CD8+ T cell survival in the process of Listeria infection." (PMID 33859648, 2021).
metastatic melanoma (4 papers, 2014 to 2025). A melanoma that has spread from its primary site to another anatomic site. "BTLA expression has been specifically associated with improved clinical responses in patients undergoing adoptive T-cell therapy for metastatic melanoma." (PMID 39796775, 2025). "Higher expression of HVEM on cancer cells and higher expression of BTLA on tumor-infiltrating lymphocytes (TILs) in metastatic melanoma patients was reported." (PMID 38835768, 2024). "The multivariate Cox regression model revealed that BTLA was an independent survival indicator in metastatic melanoma." (PMID 33718105, 2020). "We first evaluated the influence of BTLA expression status on patient survival, including patients with primary and metastatic melanoma." (PMID 33718105, 2020).
multiple myeloma (4 papers, 2020 to 2024). "The high expression of BTLA was found in B cell lines, primarily on the multiple myeloma cells." (PMID 32775467, 2020). "Of note, similar high BTLA/HVEM mRNA expression levels were observed in CLL, acute myeloid leukemia (AML), multiple myeloma (MM) and DLBCL, suggesting that BTLA/HVEM axis may also play a role in the pathogenesis of these malignancies." (PMID 33917094, 2021).
prostate carcinoma (4 papers, 2020 to 2024). A carcinoma that arises from epithelial cells of the prostate gland. "Here, we first showed that HVEM and BTLA mRNA expression levels were associated with a worse progression-free interval in patients with prostate adenocarcinomas, indicating a detrimental role for the HVEM/BTLA immune checkpoint during prostate cancer progression." (PMID 34208480, 2021). "In this study, we performed gene expression analysis on peripheral blood from prostate cancer patients obtained post- radiotherapy and showed that 6 genes, including CCR7, FCGR2B, BTLA, CD6, CD3D, and CD3E, were down-regulated by a range of 1.5–2.5-fold as compared to pre-radiotherapy samples." (PMID 36291815, 2022). "In this study, we performed next-generation sequencing-based gene expression analysis in peripheral blood from prostate cancer patients obtained pre- and post-radiotherapy and found six independently down-regulated genes including CCR7, FCGR2B, BTLA, CD6, CD3D, and CD3E." (PMID 36291815, 2022). "Therefore, we explored the expression of inhibitory receptors in CD8+ T cells in prostate cancers including PD-1, LAG3, TIM-3, TIGIT, and BTLA." (PMID 32850758, 2020).
psoriasis (4 papers, 2021 to 2025). An autoimmune condition characterized by red, well-delineated plaques with silvery scales that are usually on the extensor surfaces and scalp. "BTLA-deficient animal models have been shown to have a dysregulated proportion of inflammatory γδT cells and were susceptible to psoriasis and severe skin inflammation." (PMID 33732249, 2021). "BTLA expression was also increased in NK cells from psoriasis patients compared to healthy controls (p<0.05)." (PMID 40391222, 2025). "Recent study showed that the gene expression of CD160 and BTLA was significantly lower in psoriasis patients with health control." (PMID 34354596, 2021). "While CD28, TIGIT, BTLA and PD-1 are expressed by CD8 T cells, the costimulatory receptors LIGHT and CD134 are minimally expressed in both psoriasis patients and healthy controls (<2%)." (PMID 40391222, 2025). "Thus, BTLA may be a potential target for the treatment of psoriasis." (PMID 33732249, 2021). "In summary, our data demonstrate increased BTLA expression in CD8 effector T cells and reduced PD-1 expression in all CD3-expressing subpopulations of patients with mild-to-moderate psoriasis, suggesting possible variation in T cell function if these co-inhibitory receptors are engaged." (PMID 40391222, 2025). "However, the mechanism that CD160/BTLA pathway acts as a role in the pathogenesis of psoriasis is not clear." (PMID 34354596, 2021).
tuberculosis (4 papers, 2019 to 2024). A chronic, recurrent infection caused by the bacterium Mycobacterium tuberculosis. "The researches on the role of BTLA in pulmonary infection mainly focused on tuberculosis (TB) infection." (PMID 34163466, 2021). "In contrast to the up-regulation of BTLA expression in circulating CD4+ and CD8+ T cells, APCs, and DCs, the expression of BTLA was decreased in αβ T cells of active pulmonary tuberculosis patients and anti-tuberculosis drugs induced BTLA expression along with bacterial clearance." (PMID 34163466, 2021).
Acute hepatitis (3 papers, 2019 to 2021). Acute hepatic injury resulting from inflammation typically accompanied by increased serum alanine transaminase activity. "In a Con A challenge model of acute hepatitis, BTLA-/- mice showed reduced survival and increased early secretion of serum cytokines, which was partly due to the negative regulation of NKT cells by BTLA." (PMID 33859648, 2021). "Although its ligand HVEM functions as a bidirectional switch in T cells, whereby the outcome depends on the receptors engaged, the functional consequence of CD160/BTLA/HVEM interactions in NKT cells is co-inhibitory, with deficiency aggravating NKT-mediated acute hepatitis." (PMID 31332204, 2019). "Interestingly, CD160−/− NKT cells downregulated surface BTLA during acute hepatitis." (PMID 31332204, 2019). "Furthermore, both BTLA and CD160 are expressed by iNKT cells, and both molecules served to attenuate production of inflammatory cytokines by iNKT cells during αGalCer-induced acute hepatitis, providing an example in which two HVEM-binding IgSF molecules are required in one cell type." (PMID 34709351, 2021). "Here, we present data showing that the CD160/HVEM signaling axis delivers a BTLA-independent negative signal to NKT cells in both α-GalCer and Con A-induced acute hepatitis." (PMID 31332204, 2019).
acute myeloid leukemia (3 papers, 2017 to 2025). Acute myeloid leukemia (AML) is a group of neoplasms arising from precursor cells committed to the myeloid cell-line differentiation. "Elevated BTLA expression has been reported in PBMCs from acute myeloid leukemia patients compared to healthy controls." (PMID 41300994, 2025).
asthma (3 papers, 2014 to 2025). "A research with children found that the variation of multi-loci on BTLA gene could influence serum IgE levels, which indirectly indicated that BTLA might be associated with asthma." (PMID 34163466, 2021). "Our findings establish BXD75 mice as a model for steroid-resistant asthma and demonstrate that BTLA agonism attenuates airway hyperreactivity and lung inflammation, highlighting it as a potential therapeutic strategy." (PMID 40226621, 2025). "A strong correlation between BTLA expression and both asthma severity and IL-17 levels was recently reported." (PMID 40226621, 2025). "This suggests that not only can BTLA control Th2 and Th17 inflammatory responses in asthma, but it can also modulate Th17 differentiation." (PMID 40226621, 2025). "This strain has provided valuable insights into the therapeutic potential of inducing BTLA inhibitory signaling as a treatment strategy for steroid-resistant asthma." (PMID 40226621, 2025). "Although BTLA-HVEM complexes have been shown to negatively regulate T-cell immune responses, the expression of BTLA on asthma-related basophils, eosinophils, and bronchial epithelial cells have not been investigated." (PMID 24782592, 2014). "Therefore, we reasoned that inducing BTLA inhibitory signaling with a BTLA agonist may alleviate steroid-resistant airway inflammation and AHR as previously demonstrated in experimental asthma models." (PMID 40226621, 2025).
atherosclerosis (3 papers, 2022 to 2025). A disease characterized by the build-up of fatty material and calcium deposition in the arterial wall resulting in partial or complete occlusion of the arterial lumen. "The expression of GITR, TIM-3, LAG-3 and BTLA on T cells was also examined, as these checkpoints have previously been implicated in atherosclerosis." (PMID 40761788, 2025). "In recent years, there have been few studies on the role of B7-H4 and BTLA in atherosclerosis." (PMID 36397436, 2022). "In addition, BTLA expression was significantly reduced in both blood samples and atheroma plaques from CKD-accelerated atherosclerosis mouse models, as well as in macrophages treated with uremic serum." (PMID 39926714, 2024).
autoimmune hepatitis (3 papers, 2012 to 2021). Hepatitis caused by autoantibodies. "We have shown that the deficiency of BTLA also causes the breakdown of self-tolerance, resulting in the development of an autoimmune hepatitis- (AIH-) like disease and lymphocytic infiltration in multiple organs." (PMID 22997525, 2012). "◾ The expression of BTLA is decreased in MS and SLE patients, and increased in RA patients.◾ Decreases susceptibility to EAE, autoimmune hepatitis, and autoimmune diabetes in mice." (PMID 33859648, 2021). "BTLA-deficient mice also present increased susceptibility to EAE and mice deficient in either BTLA or HVEM present heightened T cell and NKT cell responses to Con A and exhibit increased morbidity and mortality to Con A-mediated T cell-dependent autoimmune hepatitis." (PMID 26347741, 2015).
celiac disease (3 papers, 2022 to 2025). An autoimmune genetic disorder with an unknown pattern of inheritance that primarily affects the digestive tract. "In addition, we have also published data analysis-based studies on celiac disease in which we highlighted the importance of the B and T lymphocyte associated (BTLA) gene, and programmed cell death 1 ligand 1 (CD274 antigen) in ulcerative colitis." (PMID 39194989, 2024). "BTLA was further analyzed, and gene expression levels were confirmed to be overexpressed in celiac disease (p < 0.001)." (PMID 41153806, 2025). "At the protein level in our series, high BTLA expression was confirmed in celiac disease cases (p = 0.036)." (PMID 41153806, 2025). "Celiac disease was characterized by high BTLA, expressed by inflammatory cells of the lamina propria." (PMID 36011206, 2022). "The results showed that celiac disease was characterized by a higher frequency of BTLA-positive cells than controls: 70% ± 22.2 vs. 45.6% ± 12.6, respectively (p < 0.001)." (PMID 36011206, 2022). "A direct comparison of the gene expression of BTLA between celiac disease and control was statistically significant: 7.8 ± 4.4 vs. 3.7 ± 2.8 (p < 0.001)." (PMID 36011206, 2022). "In this research, celiac disease was characterized by increased expression of BTLA in the lamina propria." (PMID 36011206, 2022). "BTLA was analyzed at protein level by immunohistochemistry in an independent series of 16 celiac disease patients (with a total of 57 biopsies) and 16 small intestine controls (16 biopsies)." (PMID 36011206, 2022). "Celiac disease was characterized by high expression of BTLA both at the gene expression level, and at protein level by immunohistochemistry in a validation series." (PMID 36011206, 2022). "Among these, we confirmed that celiac disease is characterized by increased BTLA expression." (PMID 36011206, 2022). "In the celiac disease cases, four biopsies were excluded from the analysis as BTLA expression was completely absent (0% of positive cells in the inflammatory infiltrate of the lamina propria) without the presence of internal controls." (PMID 36011206, 2022).
chronic hepatitis B (3 papers, 2012 to 2024). "Of note, a single nucleotide polymorphism (SNP) of BTLA, rs76844316, was reported to protect against chronic hepatitis B infection." (PMID 30984188, 2019). "In this study, the expression of BTLA and HVEM in liver tissues from HBV-ACLF, chronic hepatitis B (CHB) patients and healthy individuals was analyzed by immunohistochemistry." (PMID 23067542, 2012). "We found that the mean fluorescence intensity (MFI) and frequency of BTLA expression in peripheral blood CD4+ T cells (but not on CD8+ T cells) were significantly upregulated in patients with HBV-ACLF compared with NC and patients with chronic hepatitis B (CHB)." (PMID 38418488, 2024).
colon carcinoma (3 papers, 2020 to 2023). "Seven checkpoint-related genes (BTLA,CD80, CD86, CTLA4, IDO1, PDCD1LG2, and TIGIT) had decreased expression in the KRAS-mutated group, providing potential opportunities for immunotherapy in colon cancer." (PMID 33254149, 2020). "Some checkpoint-related genes (BTLA, CD80, CD86, CTLA4, IDO1, PDCD1LG2, and TIGIT) had decreased expression in the KRAS-mutated group, providing potential opportunities for immunotherapy in colon cancer." (PMID 33254149, 2020).
experimental autoimmune encephalomyelitis (3 papers, 2013 to 2022). An autoimmune demyelinating disease of the central nervous system that is produced experimentally in animals by the injection of homogenized brain or spinal cord in Freund's adjuvant. "BTLA-deficient mice have increased specific antibody responses and enhanced sensitivity to experimental autoimmune encephalomyelitis (Uniprot)." (PMID 36011206, 2022). "In addition, both HVEM and BTLA-deficient mice have a higher susceptibility to experimental autoimmune encephalomyelitis, while the loss of BTLA dramatically accelerated partially MHC-mismatched cardiac allograft rejection and prolonged airway inflammation." (PMID 24205057, 2013).
follicular lymphoma (3 papers, 2020 to 2025). Follicular lymphoma is a form of non-Hodgkin lymphoma characterized by a proliferation of B cells whose nodular structure of follicular architecture is preserved. "Given that BTLA is engaged by HVEM in lymphocytes and follicular lymphoma, as the similarly observed effects of BTLA and HVEM on cancer cells, we further investigated whether tumor cell-intrinsic BTLA was also engaged by HVEM to regulate the cell growth and signaling pathway." (PMID 36552785, 2022).
influenza (3 papers, 2015 to 2022). An acute viral infection of the respiratory tract, occurring in isolated cases, in epidemics, or in pandemics; it is caused by serologically different strains of viruses (influenzaviruses) designated A, B, and C, has a 3-day incubation period, and usually lasts for 3 to 10 days. "In our study, individuals on NSAIDs also had increased levels of BTLA on their naïve mature B-cells, which is linked to higher and more sustained Ab responses to influenza vaccination." (PMID 30186359, 2018). "To observe the correlation of CRP with the local immune response of lung in mice to influenza infection, we quantified the relative expression levels of 6 immune checkpoint mRNAs in lung tissues of mice, including GITR, BTLA, TIM-3, PD-1, CTLA-4, and LAIR-1." (PMID 36275680, 2022).
leukemia (3 papers, 2015 to 2023). A malignant (clonal) hematologic disorder, involving hematopoietic stem cells and characterized by the presence of primitive or atypical myeloid or lymphoid cells in the bone marrow and the blood. "The authors postulate that deletions of the following genes ETV6, VPREB1, CDKN2A/B, TBL1XR1, PAX5 as well as BTLA and CD200 are very early and essential events in leukemia development." (PMID 27933341, 2016).
parasitemia (3 papers, 2012 to 2021). "Studies of BTLA-deficient mice have highlighted an important regulatory role for BTLA in limiting mucosal inflammation and autoimmunity and BTLA limits immune responsiveness to bacterial and parasitic infections, suggesting a classical inhibitory function for this CD28-family member." (PMID 23012619, 2012). "In contrast, BTLA knockout mice infected with non-lethal P. yoelii, exhibited strongly reduced parasitemia and cleared the infection earlier compared with wild-type mice." (PMID 30631323, 2018).
renal carcinoma (3 papers, 2022 to 2025). A carcinoma arising from the epithelium of the renal parenchyma or the renal pelvis. "In renal cancers, the main contributors to PC-1, the axis separating healthy and sick – were the CD86, TIGIT, ICOS, and BTLA genes." (PMID 40788962, 2025). "Given the negative correlation of CD160 expression with clinical prognosis in ESCC and other tumours such as renal cancer, we postulate that CD160-expressing cancer cells could use the HVEM and BTLA inhibitory pathways to inhibit T and NK cells activities." (PMID 39419971, 2024).
squamous cell carcinoma (3 papers, 2021 to 2024). A carcinoma arising from squamous epithelial cells. "The BTLA rs16859629 polymorphism increased the risk of the development of squamous cell carcinoma (CC vs. TT: adjusted OR = 9.85, 95%CI = 1.37‐71.03, and P = 0.023; CC vs. TT/TC: adjusted OR = 9.55, 95%CI = 1.32‐68.66, and P = 0.025)." (PMID 33564688, 2021). "The results showed that AA genotype of BTLA rs2171513 polymorphism might be considered as a susceptibility factor for the development of squamous cell carcinoma (SCC) (AA/GA: OR = 0.67, 95%CI = 0.45‐0.99, and P = 0.044)." (PMID 33564688, 2021).